FGF1 (fibroblast growth factor 1)
Diseases named in the same sentence as FGF1 in open-access papers (continued):
Sharing a sentence is not in itself a finding about the gene and the disease.
eosinophilic esophagitis (1 paper, 2015). Eosinophilic esophagitis (EoE) is a chronic, allergic disease of the esophagus characterized clinically by symptoms of esophageal dysfunction (including vomiting, dysphagia, feeding disorders, food impaction and abdominal pain) which persist after treatment with proton pump inhibitors (PPIs). "Subsequently, upregulation of FGF-1 was described in allografts undergoing chronic rejection and in renal inflammation, while elevated levels of circulating FGF-2 were reported in patients with inflammatory bowel disease and eosinophilic esophagitis." (PMID 25638171, 2015).
facioscapulohumeral muscular dystrophy (1 paper, 2007). An autosomal dominant disorder affecting the skeletal muscles of the face, scapula, and upper arm. "Expression of FGF-1 and 2 is significantly increased in the muscle fibers of facioscapulohumeral muscular dystrophy (FSHD)." (PMID 17425786, 2007).
Follicular Cyst (1 paper, 2023). Cyst due to the occlusion of the duct of a follicle or small gland. "FGF7 regulated the PPAR signaling pathway (FABP5 and SCD) and the MAPK signaling pathway (FGF1, FGFR2, IL1A, TGFB1, and CSF1) and pathways in cancer (IL7, CD44, SMAD2, and MMP2) may be involved in the formation of follicular cysts." (PMID 38274662, 2023).
Fuchs' endothelial dystrophy (1 paper, 2024). Fuchs endothelial corneal dystrophy (FECD) is the most frequent form of posterior corneal dystrophy and is characterized by excrescences on a thickened Descemet membrane (corneal guttae), generalized corneal edema, with gradually decreased visual acuity. "The use of FGF-1 in Descemet stripping only (DSO) for treating Fuchs endothelial dystrophy has been previously explored and has shown outstanding results in clearing corneas." (PMID 39188872, 2024).
gastric tumors (1 paper, 2025). "Future studies are needed to evaluate whether the co-expression of FGF1 and FGFR2 may characterize a specific tumor subtype, such as FGFR2-amplified gastric tumors or aggressive neuroendocrine tumors." (PMID 40806365, 2025).
hair loss (1 paper, 2015). "Nevertheless, the effect of FGF-1, FGF-2, and FGF-10 in the therapy of hair loss is confirmative and feasible." (PMID 25685806, 2015).
Hallux valgus (1 paper, 2021). Lateral deviation of the great toe (i.e., in the direction of the little toe). "Then we examined the mRNA levels of FGF family, FGF1, FGF4, FGF7, FGF8, FGF9 and found the high mRNA level of FGF9 in hallux valgus patients." (PMID 33456347, 2021).
Hartsfield-Bixler-Demyer syndrome (1 paper, 2025). "Hartsfield-Bixler-Demyer Syndrome, also known as fibroblast growth factor 1 (FGFR1)-related Hartsfield Syndrome, is a rare genetic disorder characterized by a combination of holoprosencephaly and ectrodactyly spectrum disorder, as well as facial anomalies including cleft lip and palate." (PMID 40370525, 2025).
herpes infection (1 paper, 2021). "However, the role of FGF-1 on inflammation induced by herpes infection is not currently known." (PMID 34054858, 2021).
intrahepatic cholestasis (1 paper, 2019). A cholestasis characterized by impairment of the bile flow caused by obstruction located in the liver. "Here, we firstly identified that paracrine FGF1 was selectively downregulated in the liver of ANIT-induced intrahepatic cholestasis mice." (PMID 31920680, 2019). "In our study, we identified that paracrine fibroblast growth factor 1 (FGF1) was selectively downregulated in the liver of alpha naphthylisothiocyanate (ANIT)-induced intrahepatic cholestasis mice, suggesting a pathological relevance of this paracrine FGF with abnormal BA metabolism." (PMID 31920680, 2019).
Kawasaki disease (1 paper, 2022). A rare inflammatory disease characterized by an acute febrile, systemic, self-limiting, medium-vessel vasculitis primarily affecting children. "In conclusion, bioinformatics analysis and computer simulation research indicated that CTSG, ELANE, and FGF1 were key targets of aspirin in Kawasaki disease." (PMID 35990842, 2022). "In the study, 13 core targets (such as CTSG, ELANE, and FGF1) highly related to Kawasaki disease and aspirin were identified by bioinformatics method." (PMID 35990842, 2022). "Molecular docking indicated that aspirin had close binding sites to CTSG, Elane, and FGF1 in Kawasaki disease." (PMID 35990842, 2022). "The binding energy of FGF1 was -6.98 kcal/mol, so FGF1 is a key target of aspirin in the treatment of Kawasaki disease and plays an important role in the recovery of Kawasaki disease." (PMID 35990842, 2022). "Therefore, we propose that aspirin blocks multiple inflammation pathways by acting on FGF1 and plays a role in the remodeling of damaged blood vessels in Kawasaki disease." (PMID 35990842, 2022). "The experimental results suggested that aspirin can treat Kawasaki disease by regulating inflammatory response by acting on CTSG, FGF1, and ELANE." (PMID 35990842, 2022). "We find that aspirin treats Kawasaki disease through CTSG, ELANE, and FGF1." (PMID 35990842, 2022). "In the treatment of Kawasaki disease, aspirin may regulate inflammatory response and vascular remodeling through CTSG, ELANE, and FGF1." (PMID 35990842, 2022).
kidney cancer (1 paper, 2021). Primary or metastatic malignant neoplasm involving the kidney. "Moreover, Oncomine analysis revealed that although FGF1 expression various in different human cancers, multiple previous studies supported the FGF1 loss of expression in kidney cancers." (PMID 33865387, 2021).
lipidosis (1 paper, 2022). "Beyond our hypothesis, effects of treatment were clearly multifactorial and, in part, appeared to be associated with an increased expansion of VAT involving the modulation of growth factors such as IGF1 and FGF1, ECM organization through TIMP4, and lipidosis." (PMID 35737302, 2022).
liver failure (1 paper, 2020). A liver disease characterized by the liver losing or has lost all of its function. "A potential cytoprotective effect of FGF-1 and -2 during liver regeneration was discussed since mice lacking the FGF1R and FGF2R showed impaired cytochrome P450 expression, liver failure, and increased mortality after liver resection." (PMID 32050952, 2020).
mantle cell lymphoma (1 paper, 2023). Mantle cell lymphoma is a rare form of malignant non-Hodgkin lymphoma affecting B lymphocytes in the lymph nodes in a region called the ``mantle zone''. "In SOX11-positive mantle cell lymphoma, increased tumor angiogenesis and higher levels of pro-angiogenic factors, including angiopoietin-1 and -2 and fibroblast growth factor-1, were observed." (PMID 37391758, 2023).
mastitis (1 paper, 2023). Inflammation of breast tissue during lactation or postpartum due to an obstructed duct or infection. "The FIBP binds fibroblast growth factor 1 (FGF1), which is involved in defense mechanisms against bacterial invasion in mastitis." (PMID 37685039, 2023).
meningioma (1 paper, 2022). A generally slow growing tumor attached to the dura mater. "Importantly, FGFR2 and FGFR3 were detected in meningiomas, and FGF1 was shown to be able to stimulate meningioma cell proliferation by activation of AKT1 and STAT3." (PMID 35996584, 2022).
metastatic melanoma (1 paper, 2017). A melanoma that has spread from its primary site to another anatomic site. "Furthermore, using this chaperone, we revealed a link between the UPR and fibroblast growth factors, as FGF1 and FGF2 are up-regulated in metastatic melanoma cells and can be reduced after 4-PBA treatment." (PMID 29235576, 2017).
Nephroblastoma (1 paper, 2013). An embryonal neoplasm characterized by the presence of epithelial, mesenchymal, and blastema components. "Acidic fibroblast growth factor, FGF1 (−2.96) and FGF7 (−1.473) were also down-regulated, as well as NOV-like CTGF- member of the CCN protein family: nephroblastoma overexpressed/NOV (−3.149)." (PMID 24344983, 2013).
neuroblastoma (1 paper, 2017). Neuroblastoma (NB) is the most common solid, extracranial childhood tumor. "To progress in the characterization of FGF1 anti-apoptotic activity in human neuroblastoma, we transfected SH-SY5Y cells with different mutated forms of FGF1 (that is, FGF1K132E, FGF1S130A and FGF1S130D)." (PMID 29048426, 2017). "Using different FGF1 mutants (that is, FGF1K132E, FGF1S130A and FGF1S130D), we further showed that the C-terminal domain and phosphorylation of FGF1 regulate its intracrine anti-apoptotic activity in neuroblastoma SH-SY5Y cells." (PMID 29048426, 2017). "The study of FGF1 expression and activity must be pursued in a large panel of neuroblastoma tumors and cell lines." (PMID 29048426, 2017). "The FGF1 anti-apoptotic activity was detected in human neuroblastoma SH-SY5Y cells, in rat neuron-like PC12 cells and in rat REtsAF fibroblast, suggesting that this effect is conserved in different cell types and mammalian species." (PMID 29048426, 2017). "The regulation of fgf1 expression after rFGF1 or etoposide treatment also differed between the two neuroblastoma cell lines." (PMID 29048426, 2017). "However, no activity of either extra- or intra-cellular FGF1 could be detected in the mouse neuroblastoma N2a cell line, suggesting that this neuroblastoma-derived cell line was impaired in the FGF1 anti-apoptotic signaling pathway." (PMID 29048426, 2017). "We focused on the activity of either extracellular FGF1 by adding recombinant rFGF1 in media, or of intracellular FGF1 by overexpression in human SH-SY5Y and mouse N2a neuroblastoma cell lines." (PMID 29048426, 2017). "After heparin-sepharose, endogenous FGF1 could be detected only in cell lysates, suggesting that endogenous FGF1 is also non-secreted in neuroblastoma SH-SY5Y cells." (PMID 29048426, 2017).
nonalcoholic steatohepatitis (1 paper, 2023). "Our recent study demonstrated that FGF1ΔHBS, a non-mitogenic variant of native FGF1, prevented high fat and high cholesterol (HFHC) diet-induced nonalcoholic steatohepatitis (NASH) in ApoE knockout (ApoE-KO) mice and reversed the established NAFLD in late stage db/db type 2 diabetic mice." (PMID 37999577, 2023).
oral cancers (1 paper, 2023). "Activating mutations in the NOTCH1 gene and increased transcription of the FGF1 (Fibroblast Growth Factor 1) gene result in increased cell migration and invasiveness and increased mortality in patients with oral cancers." (PMID 38179168, 2023).
otitis media (1 paper, 2020). Inflammation of the anatomical structures of the middle ear, which is most often caused by an infectious process. "FGF1 also contributed to the increased number of blood vessels in the middle ear mucosa during otitis media." (PMID 32210827, 2020).
ovarian tumors (1 paper, 2018). "Our purpose was to understand the role of FGF1 in chemoresistance in ovarian tumors." (PMID 29467390, 2018).
peripheral artery disease (1 paper, 2024). "FGF-1 (Acidic Fibroblast Growth Factor) gene therapy delivers the FGF-1 gene, aims to enhance angiogenesis, and has been tested in clinical trials for treating coronary and peripheral artery disease." (PMID 39063029, 2024).
presbycusis (1 paper, 2022). Bilateral hearing loss caused by progressive degeneration of cochlear structures and central auditory pathways, typically associated with the aging process. "In the GSE49543 data set, four genes (Ywhag, Mapre2, Fgf1, Acss2) were used to construct the prognostic model, and those four genes were significantly up-regulated in the rat model of presbycusis." (PMID 35463035, 2022).
psychosis (1 paper, 2023). "GADD45β has been shown to regulate activity-dependent DNA demethylation at specific loci in genes like BDNF and fibroblast growth factor 1 (Fgf1) that have been implicated in neurogenesis, synaptic plasticity, and psychosis." (PMID 36781843, 2023).
pulpitis (1 paper, 2021). Inflammation of the dental pulp. "FGF1 significantly increased in the dentinal fluid of irreversible pulpitis compared to reversible pulpitis or normal pulp." (PMID 38947881, 2021).
renal carcinoma (1 paper, 2021). A carcinoma arising from the epithelium of the renal parenchyma or the renal pelvis. "PTPRO and FGF1 were already established prognostic biomarkers of renal cancers." (PMID 34557161, 2021).
retinoblastoma (1 paper, 2022). A malignant tumor that originates in the nuclear layer of the retina. "Regarding other ocular neoplasms, scattered evidence obtained on human retinoblastoma cell lines showed the expression of all four FGFRs, with cell proliferation in response to stimulation with FGF1 and FGF2." (PMID 35409195, 2022). "Moreover, experimental evidence shows that treatment with exogenous FGF1 induces the activation and phosphorylation of FGFR1 in the human retinoblastoma Y-29 cell line, while the selective inhibition of FGFR1 resulted in decreased cell proliferation." (PMID 35409195, 2022).
salivary gland tumors (1 paper, 2021). "It has also been demonstrated that malignant salivary gland tumors and SGC cells contain high levels of FGF-1." (PMID 35012286, 2021).
schizophrenia (1 paper, 2014). A major psychotic disorder characterized by abnormalities in the perception or expression of reality. "The SEC24C gene is associated with neurotransmitter transporters, while FGF1 and S100 family are related to schizophrenia." (PMID 25522158, 2014). "SNPs in FGF1 were reported to be associated with the risk of developing schizophrenia." (PMID 25522158, 2014).
Sciatica (1 paper, 2021). Pain in the lower back and hip radiating in the distribution of the sciatic nerve. "AZU1, BPI, TCF7L2, and WFIKKN1 were upregulated in sciatica patients, while ANGPTL4, CRP, EREG, FAM19A4, FGF1, LOC100129216, PLXNB1, RLN1, and RXFP2 were downregulated." (PMID 34925462, 2021).
serous ovarian tumors (1 paper, 2018). "Overexpression of Fibroblast Growth Factor 1 (FGF1) has been linked to high grade serous ovarian tumors and poor survival." (PMID 29467390, 2018).
steatosis (1 paper, 2021). Increased lipid within the cytoplasm of cells. "As shown in H&E staining, the liver of db/db mice showed remarkable steatosis when compared to that of db/m mice and FGF1‐treated mice." (PMID 33788387, 2021).
thyroid tumor (1 paper, 2017). A benign or malignant neoplasm affecting the thyroid gland. "FGF1 and FGF2 have been reported as over-expressed in differentiated thyroid tumors, but their receptors present contrasting results." (PMID 28469731, 2017).
uveal melanoma (1 paper, 2022). A melanoma derived from melanocytes of the uveal tract. "Expression analysis in a set of 9 primary uveal melanomas reported that FGF1 and FGF2 were expressed in 77% of samples, with co-expression of FGF1/FGF2 in 55% of cases." (PMID 35409195, 2022).